NRG1 (neuregulin 1)
Diseases named in the same sentence as NRG1 in open-access papers (continued):
Sharing a sentence is not in itself a finding about the gene and the disease.
pancreatic cancer (continued). "CAF-CM promoted pancreatic cancer cell proliferation in vitro and this effect was moderately diminished by a presence of the inhibitory NRG-1 antibody (P<0.01)." (PMID 21792199, 2011). "In addition, the observed frequencies of NRG1 fusions in other tumor types were 0.25% in esophageal cancer, 0.17% in colorectal cancer, 0.13% in gastric cancer, 0.11% in pancreatic cancer, and 0.05% in liver cancer." (PMID 40730881, 2025). "Finally, NRG1 fusion partners were most commonly ATP1B1 (pancreatic cancer) or CD74 (NSCLC) in FDA-approved indications, with a mix of these as well as SLC3A2 and RBPMS being commonly observed partner genes in nonapproved indications." (PMID 41091579, 2025). "In addition, the frequencies of NRG1 fusion in colorectal cancer, gastric cancer, pancreatic cancer, and liver cancer were lower than the overall frequency." (PMID 40730881, 2025). "Responses appear to occur in a tumor-agnostic fashion and have been described in NRG1 fusion-bearing lung, cholangiocarcinoma, ovarian, and pancreatic cancers, suggesting that malignancies harboring NRG1 fusions merit further investigation for another tissue-agnostic approval." (PMID 38369520, 2024). "Recent studies have supported the resistance to antiandrogens in the EGFR/ERK pathway through miR-146a-5p and the NRG1/HER3 axis in prostate cancer; however, obstructing NRG1/HER3 and inhibiting migration and growth strengthens ADCC in NRG1-positive pancreatic tumors and CAFs." (PMID 39075612, 2024). "Additional testing of NRG1 inhibition and resensitization to cetuximab could also be investigated using two high-affinity monoclonal antibodies to NRG1 or an anti-NRG1 antibody that has shown inhibition of tumor growth in preclinical models of pancreatic cancer." (PMID 35461210, 2022). "The response rate was 34% and median duration of response of 9.1 months across multiple NRG1 fusion bearing solid tumors (e.g., NSCLC, pancreas cancer, breast cancer, cholangiocarcinoma)." (PMID 38369520, 2024). "Targeted therapies for CAFs in pancreatic cancer include focal adhesion kinase (FAK), neuregulin 1 (NRG1), LRRC15+ CAFs, etc., The FAK inhibitor suppressed tumor cells and CAFs in a mouse model." (PMID 34336821, 2021). "When applied to a large collection of published pancreatic cancer samples (n = 803), Arriba identified a variety of driver fusions, many of which affected druggable proteins, including ALK, BRAF, FGFR2, NRG1, NTRK1, NTRK3, RET, and ROS1." (PMID 33441414, 2021). "Consistently, direct activation of either ErbB3 or EGFR signaling with specific ligands (NRG-1 and EGF, respectively) also resulted in significant abrogation of anti-pancreatic cancer activity of VPA." (PMID 30961642, 2019). "Pretreatment with MM-121 followed by NRG-1 stimulation rendered ligand-induced ErbB3 activation ineffective and combination of MM-121 with erlotinib completely abolished AKT activation in pancreatic cancer cells." (PMID 21792199, 2011). "Notably, the most common non–FDA-approved indications were cancers with limited targeted therapies available: pancreatic cancer for FGFR2 fusions (prevalence of 0.5%) and prostate cancer for FGFR3 and NRG1 fusions (combined prevalence of 0.4%)." (PMID 41091579, 2025). "We conclude that stromal CAF-secreted NRG-1 stimulates ErbB3/AKT signalling and promotes pancreatic cancer cell tumourigenesis, providing a mechanism that may contribute to PDAC resistance to anti-EGFR therapy." (PMID 21792199, 2011). "Based on novel gene fusions involving NRG1 that we recently discovered in a series of patients with KRAS wild-type pancreatic tumors in the context of NCT/DKTK MASTER, a HTS-guided precision oncology program, we applied Arriba to further explore the relevance of gene fusions in pancreatic cancer." (PMID 33441414, 2021).
pancreatic cancer (continued). "Nevertheless, our findings confirm without a doubt the presence of CAF-secreted NRG-1 and the stimulatory effects of this ligand on ErbB3 signalling and proliferation of pancreatic cancer cells, further supporting the hypothesis of active stromal–epithelial interaction in PDAC." (PMID 21792199, 2011). "Overall, 13.6% and 8.2% of FGFR2 fusions were in nonapproved breast and pancreatic cancer indications, respectively, 22.2% of FGFR3 fusions were in nonapproved NSCLC, and 19.4% and 10.2% of NRG1 fusions were in nonapproved breast and prostate cancers, respectively." (PMID 41091579, 2025).
heart failure (37 papers, 2008 to 2026). Inability of the heart to pump blood at an adequate rate to meet tissue metabolic requirements. "Recent studies have revealed the mechanism underlying the therapeutic effects of NRG-1/ErbB signaling in the treatment of heart failure." (PMID 38553458, 2024). "The development of dilated cardiomyopathy in ErbB2-deficient mice and anti-HER2 (ErbB2)-targeted therapy patients suggests that the NRG-1/ErbB signaling pathway is implicated in the pathophysiology of heart failure." (PMID 38132657, 2023). "For example, the levels of NRG1 Type I were decreased in diabetic rats with cardiomyopathy and impaired signaling through the NRG1/Erb B cassette may contribute to the pathogenesis of diabetic cardiomyopathy, increasing susceptibility to heart failure." (PMID 24252174, 2013). "Based on these and other findings, clinical trials evaluating the efficacy of NRG1 in patients with heart failure have been conducted." (PMID 41191311, 2026). "Recent studies have shown that NRG-1 plays an important role in the occurrence and development of CVDs, such as heart failure (HF), myocardial infarction (MI)/ischemia‒reperfusion (IR), atherosclerosis, cardiotoxicity and arrhythmia." (PMID 40747492, 2025). "Circulating Nrg1 also rises with heart-failure severity, consistent with a compensatory response to stress." (PMID 41256601, 2025). "Neuregulin-1 (NRG1): In heart failure, NRG1 activity increases as a compensatory mechanism to mitigate cardiac remodeling and disease progression." (PMID 40227326, 2025). "Exposure to recombinant human NRG-1 restores mitochondrial membrane potential, respiration rate, and ATP concentration in cardiomyocytes and skeletal muscle cells in an animal model of heart failure." (PMID 38562689, 2024). "A phase 1, double blind, placebo-controlled, single ascending dose study examined the safety, tolerability, and exploratory efficacy of intravenous infusion of recombinant NRG-1/Cimaglermin alfa, in patients with heart failure." (PMID 38638304, 2024). "Two additional clinical trials to determine the ability of NRG-1/Neucardin to improve cardiac function after heart failure have been initiated in the U.S. (ClinicalTrails.gov identifiers NCT02664831; NCT01258387)." (PMID 38638304, 2024). "Proteins ErbB2 and ErbB4, downstream of NRG-1, have demonstrated mitigation of heart failure and, when activated to heterodimerize, trigger MAPK signaling." (PMID 37856516, 2023). "The NRG-1/ErbB4 signalling system is critical for the mitigation of heart failure, an outcome of late-stage CAD." (PMID 37336921, 2023). "ErbB signaling is essential in cardiac development and cardiovascular homeostasis, which serve as receptors mediating the biological effects of neuregulin-1 (NRG-1), a protective factor in heart failure." (PMID 37234159, 2023). "Prior studies have shown the following: NRG1 undertakes anti-fibrotic and anti-remodeling actions in heart failure models, it protects myocardial cells from damage and it improves cardiac function." (PMID 36012430, 2022). "We previously reported results from a pre-clinical trial of the effects of a pharmaceutical grade of NRG-1/GGF2 (cimaglermin alfa) using a swine model of heart failure." (PMID 35625411, 2022). "In conclusion, despite NRG-1’s established function in heart failure, all available evidence strongly suggests that it also has a role in acute MI in humans, making STEMI patients an additional target population for research." (PMID 36012430, 2022). "In cases of heart failure, NRG1/ErbB signaling is significantly impaired, and administration of NRG1 attenuates the progression of HF, inhibits myocardial fibrosis and apoptosis, and reduces oxidant-producing enzymes." (PMID 36120374, 2022). "Numerous experiments have shown that NRG1 can repair the heart in the pathophysiology of atherosclerosis, myocardial infarction, ischemia reperfusion, heart failure, cardiomyopathy and other cardiovascular diseases." (PMID 36120374, 2022).
heart failure (continued). "In the specific example of heart failure, when cardiomyocytes are injures or overloaded, NRG1 expression increases, leading to fibroblast and macrophage activation." (PMID 34680187, 2021). "Currently, there are multiple clinical trials ongoing attempting to either target or amplify NRG1 for different conditions such as heart failure and multiple neoplasia." (PMID 34680187, 2021). "Nrg1 null mice die mid‐gestation (E10.5) from cardiac failure due to the poor development of these ventricular trabeculae, as well as endocardial cushion defects." (PMID 36618440, 2021). "NRG1 is currently in a phase III human clinical trial for heart failure and showed significant efficacy for improving cardiac function human patients." (PMID 29856744, 2018). "Administration of NRG-1 improved cardiac function via SERCA2a and cMLCK in a rat heart failure model." (PMID 30134819, 2018). "NRG-1 has been used in many animal models of heart failure and is currently tested in phase III clinical trial in heart failure with a reduced left ventricular ejection fraction." (PMID 27596216, 2016). "The NRG-1/ErbB signaling axis is activated in heart failure, and compensates for maladaptive processes that lead to the progression of cardiac dysfunction, at least during the early stages of the syndrome." (PMID 27596216, 2016). "Two additional clinical trials to determine the ability of NRG-1 to improve cardiac function after heart failure have been initiated in the US (ClinicalTrails.gov identifiers NCT01258387 and NCT01541202)." (PMID 24433482, 2014). "In rat cardiomyocytes, neuregulin-1 activates endothelial nitric oxide synthase, and there is evidence that the nitric oxide synthase has a role in both heart failure and atherosclerosis." (PMID 18798975, 2008). "A recent study in mice investigated the role of NRG1-mediated activation of erythroblastic leukemia viral oncogene homolog ERBB4 receptors in cardiomyocytes in a transverse aortic constriction (TAC) model of heart failure." (PMID 40227326, 2025). "This has led to studies in which NRG1 is administered to patients with heart failure, improving cardiac function in different models, and is currently being researched in other pathologies such as atrial fibrillation as well as other cardiac diseases, such as Hirschsprung’s disease." (PMID 34680187, 2021). "Many studies have shown the potential effects of NRG-1 on heart failure." (PMID 30134819, 2018). "The protective effect of Neuregulin-1 (NRG-1) on heart failure is well established." (PMID 30134819, 2018). "If confirmed in humans, on top of the standard therapy, NRG-1 treatment may take a particular position in the pharmacological therapy of heart failure aimed at regenerating the injured heart and mitigating its co-morbidities." (PMID 27596216, 2016). "We will address the biology of ErbB signaling in cancer and cardiac cells, the regulatory aspects and clinical benefits of NRG-1/ErbB signaling activation in heart failure, and the working mechanisms of different anti-ErbB2 drugs and their degree of cardiotoxicity." (PMID 27596216, 2016). "Recent reports have underscored the importance of the Nrg1-ErbB2/4 signaling pathway in cardiac repair processes, and recombinant Nrg1 is currently in clinical trials as a heart failure therapeutic, but the role of Nrg1 in development is largely unknown." (PMID 27846271, 2016). "Increasing the activity of the NRG1-ERBB signaling complex might provide a viable strategy for treating heart failure." (PMID 25996292, 2015). "Some clinical studies of heart failure patients, find NRG1 to be up-regulated." (PMID 22792252, 2012). "NRG-1 may induce counterbalancing parasympathetic activity in animal models, which is potentially an additional factor in the protective role of neuregulin in heart failure." (PMID 24223630, 2013).
heart failure (continued). "Exposure to recombinant human NRG-1 restores MMP, respiration rate, and ATP concentration in cardiomyocytes and skeletal muscle cells in an animal model of heart failure." (PMID 39342996, 2024). "Interestingly, another series of recent experiments indicate that, apart from healing the heart, the activation of ErbB signaling with systemic NRG-1 may also mitigate common co-morbidities of heart failure, including diabetes, atherosclerosis, pulmonary hypertension, and renal dysfunction." (PMID 27596216, 2016). "Neuregulin-1 (NRG-1), a member of epidermal growth factor family, plays a critical role for cardiomyocyte proliferation and prevention of heart failure via ErbB receptors." (PMID 27861634, 2016). "Neuregulin-1 (NRG-1), a stress-mediated paracrine transmembrane growth factor, plays vital roles in the pathophysiology of atherosclerosis, myocardial infarction, ischemia-reperfusion, heart failure (HF), cardiomyopathy and other cardiovascular diseases." (PMID 40747492, 2025). "Similarly to our results, increased expression levels of ACE2, NRG1, DUSP4 and LIF have also been found in human heart failure." (PMID 26537877, 2016).
bipolar disorder (31 papers, 2007 to 2025). A disorder of the brain that causes unusual shifts in mood, energy, activity levels and the ability to carry out day-to-day tasks. "In a previous study, polymorphic variants of NRG1 was associated with predisposition for bipolar disorder." (PMID 35208605, 2022). "For example, the leading candidate risk factor gene, NRG1, which has also been linked to bipolar disorder, is minimally expressed during late adolescence together with its ligand ERBB4." (PMID 19457239, 2009). "Time to recurrence of a depressive episode and time to recurrence of a manic or mixed episode among patients with bipolar disorder may be indicated by alleles of two different variants: rs35641374 in NRG1 and rs10508649 in PIP4K2A, respectively." (PMID 33193575, 2020). "Moreover, altered Ndst3 expression has been linked to shizophrenia and bipolar disorder, which may be linked to altered HS-dependent neuregulin-1 distribution and signaling." (PMID 32664575, 2020). "Decreased expression of neuregulin 1 has been linked to orchestration of a number of executive functions in ASD patients, as well as SCZ and bipolar disorders." (PMID 35501678, 2022). "Implication of NRG1 in the pathogenesis of depressive symptoms among patients with bipolar disorder is also supported by previous studies, linking this gene to bipolar disorder and depression." (PMID 33193575, 2020). "While findings from these studies tended to support for the role of NRG1 rs6994992 (mainly as part of haplotype) in bipolar disorder, all these studies were conducted in the European population." (PMID 31649580, 2019). "Nrg1 is a potential biomarker for various clinical subtypes of depression and bipolar disorder." (PMID 39135796, 2024). "Namely, alleles of rs35641374 and rs10508649 (NRG1 and PIP4K2A) may be prognostic biomarkers of time to recurrence of depressive and manic/mixed episodes among patients with bipolar affective disorder." (PMID 33193575, 2020). "According to the best of our knowledge, only a few studies have investigated the association between NRG1 and bipolar disorder in the Asian population (including the Han Chinese population), and none examined NRG1 rs6994992." (PMID 31649580, 2019). "Moreover, anxiety was partially improved in a small group of patients suffering from bipolar disorder in good agreement with our finding that spironolactone affects anxiety‐related behavior in Nrg1‐tg mice." (PMID 28743784, 2017). "Thus, whether NRG1 rs6994992 was also related to bipolar disorder in the Asian population remains to be elusive." (PMID 31649580, 2019). "However,recent genome-wide association analyses have not provided evidence for commonvariation in NRG1 or ERBB4 influencingschizophrenia or bipolar disorder susceptibility." (PMID 21637803, 2011). "It is worthy of note that the alleles of NRG1 and PIP4K2A may be simultaneous predictors of time to recurrence of manic and depressive episodes among patients with bipolar disorder and of absence of drug treatment response among patients with depression." (PMID 33193575, 2020).